IL24 (interleukin 24)
Diseases named in the same sentence as IL24 in open-access papers (continued):
Sharing a sentence is not in itself a finding about the gene and the disease.
tumor (continued). "In mouse PCa xenografts, IL-24 decreases the levels of secreted soluble clusterin (sCLU) protein, which is linked to resistance to chemotherapy and radiation and hormone therapies, leading to reduced tumor growth and angiogenesis." (PMID 30669553, 2019). "Since mda-7/IL-24 acts as tumor suppressor, loss of transgene expression, perhaps as a result of limited delivery of doxycycline to the tumor mass or epigenetic silencing, may promote selection of faster growing cancer cells that eventually dominate." (PMID 26460950, 2015). "This initial observation lead us to ask the question of whether IL-24 inhibited tumor vascularization and the underlying molecular mechanism?" (PMID 24377906, 2013). "In this study we report the design and validation of SM7L, a unique multifunctional molecule with potent anti-tumor effects derived from enhancement of the therapeutic cytokine MDA-7/IL-24 and diagnostic properties due to incorporation of a photon-emitting luciferase." (PMID 22808125, 2012). "Extensive research within the last decade has shown that IL-24 exhibits tumor suppression activities." (PMID 40072085, 2025). "This decrease in metastasis is possibly a consequence of the diminished abilities of tumor cells to migrate and invade after IL‐24 treatment." (PMID 40338095, 2025). "Cytokines including IL-6, IL-10, IL-11 and IL-24 can suppress immune effector cells, such as T cells, natural killer cells and dendritic cells, impairing the host’s anti-tumour response while facilitating the immune evasion of GBM cells." (PMID 41301734, 2025). "IL-24 is a member of the IL-10 cytokine family with both pro- and anti-inflammatory roles and roles in tumor suppression." (PMID 41301428, 2025). "IL24 induces selective apoptosis in tumor cells through multiple pathways, including the activation of pro-apoptotic genes and modulation of immune responses." (PMID 40076725, 2025). "In this regard, numerous studies have independently confirmed IL‐24's potential as a potent anti‐cancer agent, capable of selectively triggering apoptosis in various tumor cell types while preserving normal cells." (PMID 40338095, 2025). "Despite the evidence validating the tumor‐suppressing properties of IL‐24 in cancer models, there is a dearth of information regarding its role in other human diseases." (PMID 40338095, 2025). "In mice with tumors of TNBC, PVT significantly reduced tumor growth and the expression levels of PTP1B, CXCL12, CXCR4, PI3K, AKT, mTOR and other proteins in TNBC tumor tissue and upregulated the expression of IL-24." (PMID 40076586, 2025). "The clinical trial results finally revealed that IL‐24 exhibits pro‐immune properties, stimulating the host immune response and effectively inhibiting tumor growth across various cancer types." (PMID 40338095, 2025). "Despite numerous preclinical studies demonstrating the selective anti‐tumorigenic potential of IL‐24 in tumor cells, there has been limited progress in the last 20 years on moving IL‐24 into clinical trials." (PMID 40338095, 2025). "Upon Vin treatment, control tumors exhibited significant growth inhibition, whereas tumors with ATF3 or IL-24 knockdown showed markedly reduced sensitivity to Vin, with minimal suppression of tumor growth observed." (PMID 40866941, 2025). "In summary, these findings indicate that IL‐24 treatment has a significant effect on the T cell population to potentially result in tumor cell killing." (PMID 40338095, 2025). "The results revealed that, compared with the Mod group, the IL-24 protein levels in the tumor tissues of the PVTM, PVTH, Taxol and PVTM + Taxol groups were increased, whereas the CXCL12 protein level was decreased." (PMID 40076586, 2025). "The subsequent sections delve into the role of IL‐24 in different facets of tumor progression as well as its utility as an anti‐cancer therapeutic." (PMID 40338095, 2025). "Animals receiving the mixture of A549 cells and HEK 293 cells expressing IL‐24 exhibited a reduction in tumor growth." (PMID 40338095, 2025).
tumor (continued). "In this study, we further showed that calcipotriol-induced TSLP activates Th2 cells to release IL-4, which in turn promotes IL-24 production by TAMs, resulting in tumor cell apoptosis." (PMID 39782693, 2025). "The dual overexpression of NKG2D and IL24 enhances the specificity and efficacy of exosome-mediated anti-tumor activity, offering a promising avenue for the development of novel oncotherapy approaches." (PMID 40076725, 2025). "Despite the promising efficacy of recombinant IL-24 (rIL-24) in antitumor therapies, its clinical application is hindered by the low efficiency of tumor-targeted delivery." (PMID 40866941, 2025). "The NK-Exos engineered to express both NKG2D and IL24 significantly enhanced tumor targeting and increased the apoptosis rate of tumor cells by 30% in A549 and by 20% in HELA at 48 h compared with non-modified NK-Exos, respectively." (PMID 40076725, 2025). "Oncolytic vaccinia viruses express IL-2, IL-10, IL-12, IL-15, IL-21, IL-23, IL-24, and IL-36γ remodel the tumor microenvironment,enhance immune cell infiltration, suppress immunosuppressive elements and promot systemic antitumor immunity." (PMID 40469178, 2025). "ELISA revealed circulating IL‐24 protein in mice serum, and this secreted IL‐24 was reported to affect tumor endothelial cells and hinder angiogenesis, resulting in an anti‐tumor effect." (PMID 40338095, 2025). "While numerous studies have revealed novel pathways modulated by intracellular IL‐24, some efforts have also aimed to explore the impact of secreted IL‐24's anti‐tumor activity on neighboring cells." (PMID 40338095, 2025). "This suggests that the combination of NKG2D and IL24 is particularly effective at inhibiting the migratory potential of tumor cells." (PMID 40076725, 2025). "Microarray analyses of breast and NSCLC cell lines overexpressing IL‐24 had previously revealed upregulation in the expression of genes with tumor‐suppressing abilities such as E‐cadherin, PTEN, and GSK‐3β." (PMID 40338095, 2025). "The summarized studies provide clear evidence that IL‐24‐mediated anti‐tumor activity operates through key pathways governing cancer progression and has undergone clinical testing for cancer treatment." (PMID 40338095, 2025). "In conclusion, this study elucidates the significant role of NK92MI-derived exosomes overexpressing NKG2D and IL24 in enhancing anti-tumor efficacy against various cancer cell lines, including A549, HELA, and MCF-7." (PMID 40076725, 2025). "Western blot analysis confirmed efficient knockdown of ATF3 and IL-24 in tumor cells prior to implantation." (PMID 40866941, 2025). "The activation of antitumor CD4+T cells upon adoptive transfer of tumor-specific Tc9s occurs as a result of IL-24 secretion and recruitment of CCR7+cDC2s (conventional type 2 DCs) into tumor-draining LNs, which prime host CD4+T cells against relapsing tumors." (PMID 41009359, 2025). "IL-24 is very well known for its tumor-suppressive activity and is utilized as a therapeutic agent in cytokine therapy against a broad spectrum of cancers." (PMID 40661937, 2025). "While IL-4R signaling promotes tumor progression and immune evasion, IL-24 acts as a natural brake on tumor growth." (PMID 40508013, 2025). "IL-24 was originally identified as a tumor suppressor molecule, and then renamed IL-24 and classified as a cytokine, based on its chromosomal location in the IL-10 locus, its mRNA expression in leukocytes, and its secretory sequence elements." (PMID 39799030, 2025). "For instance, it has been reported that IL24 induces apoptosis selectively in tumor cells, sparing normal cells by acting through specific pathways that are regulated in malignancies." (PMID 40076725, 2025). "It was further documented that IL‐24 secreted from a minor subset of tumor cells was able to infiltrate the whole tumor, thus establishing the bystander effect of IL‐24." (PMID 40338095, 2025).
tumor (continued). "The addition of IL24 appears to amplify the anti-tumor effects by promoting apoptosis, inhibiting cell proliferation, and reducing migratory capacity." (PMID 40076725, 2025). "Subsequently, it was conclusively shown that IL‐24 inhibits tumor angiogenesis through both intracellular and extracellular mechanisms." (PMID 40338095, 2025). "The administration of INGN 241 resulted in the localization of IL‐24 in tumor cells, inducing tumor cell apoptosis, as indicated by the TUNEL assay." (PMID 40338095, 2025). "Recent advances highlight the complex interplay between tumor-promoting and tumor-suppressing immune signals—such as IL-4Rα-driven progression and IL-24-mediated inhibition—as well as novel targets like ERBB2 and tumor-associated autoantigens." (PMID 40508013, 2025). "A Phase I clinical trial using an adenovirus vector expressing IL-24 (Ad-IL-24) has documented the T cell activation and cytokine release for the eradication of tumor cells." (PMID 40661937, 2025). "In their study, 5 × 105 CT26 cells were injected subcutaneously followed by treatment with intravenous GST‐IL‐24 fusion protein to examine the effect of IL‐24 on immune cells and tumor growth." (PMID 40338095, 2025). "IL24 has been shown to suppress tumor invasion and metastasis by modulating matrix metalloproteinase (MMP) expression or SDF-1/CXCR4 signaling axis, while NKG2D enhances the targeting and killing of tumor cells, further reducing their ability to migrate." (PMID 40076725, 2025). "Clinicopathological indicators (age, tumor stage, nodal stage, metastasis stage) predicted poorer overall survival in those with low IL24 expression compared with those with high IL24 expression in the univariate analysis." (PMID 39782693, 2025). "The co-localization of red and green fluorescence within the tumor cells indicates that the IL24-NKG2D-Exo successfully delivered IL24 protein into A549 and HELA cells." (PMID 40076725, 2025). "A majority of studies have focused on the role of IL-24 in the pathophysiology of diseases, as this multi-functional cytokine serves as both a tumor suppressant and an agent with pro- and anti-inflammatory properties." (PMID 40661937, 2025). "IL-24’s anticancer function as a cytokine involves its interaction with the IL-20R, leading to endoplasmic reticulum stress–induced tumor cell apoptosis." (PMID 39782693, 2025). "IL-24 exerts multifaceted antitumor effects by inducing endoplasmic reticulum stress and ROS generation, thereby promoting tumor cell apoptosis, and inhibiting angiogenesis." (PMID 40866941, 2025). "For example, IL-22 promotes tumor growth by enhancing cancer cell proliferation and protecting against apoptosis, whereas IL-24 demonstrates anti-tumor activity by inducing cancer cell death and inhibiting metastasis." (PMID 40806452, 2025). "Due to its remarkable tumor-suppressing ability, IL-24 shows greater potential for advanced targeted cancer therapy." (PMID 40661937, 2025). "Studies on the role of IL-24 in cancer have shown that this cytokine can exert its tumor suppression effect through various molecular mechanisms." (PMID 40072085, 2025). "The utility of NK-Exos co-expressing NKG2D and IL24 offers a novel approach to overcome the limitations of current therapies, providing prolonged tumor suppression and precise targeting of malignant cells and holding great promise for clinical application." (PMID 40076725, 2025). "Recombinant Bifidobacterium breve-IL24 treatment exhibited significantly reduced tumor growth compared to the control group (Bifidobacterium breve-GFP)." (PMID 40805186, 2025). "The results from these in vivo studies consistently showed increased tumor cell apoptosis and a notable decrease in tumor size, thereby providing a strong rationale for utilizing IL‐24 in combination with radiation therapy to improve cancer treatment outcomes." (PMID 40338095, 2025). "IL24 inhibits MM cell tumor growth by inducing tumor cell autophagy, thus suppressing MM cell tumor growth." (PMID 40173324, 2025).
tumor (continued). "IL-24 is a versatile cytokine that can regulate anti-tumor activity, immune response, tissue homeostasis, and host defense mechanisms." (PMID 40661937, 2025). "Use of sulindac increased the half‐life of IL‐24 and increased the expression of various protein kinases and caspases, ultimately leading to greater apoptosis of tumor cells." (PMID 40338095, 2025). "Several pre-clinical and clinical studies have indicated that IL-24 exhibits tumor suppression activities." (PMID 40072085, 2025). "Th2 cell–derived cytokines upregulate anticancer IL-24 cytokine expression by TAMs to kill tumor cells." (PMID 39782693, 2025). "The selective tumor‐killing ability of IL‐24 is further substantiated by its ability to suppress NF‐κB expression in human lung tumor cells H1299 and A549." (PMID 40338095, 2025). "In vivo studies were conducted in subcutaneous xenograft tumor models established using a 1:1 ratio of human lung A549 cells with parental HEK293 cells or IL‐24 expressing HEK 293 cells." (PMID 40338095, 2025). "NKG2D facilitates the recognition of tumor cells by binding to stress-induced ligands, while IL24 induces apoptosis and modulates immune responses to enhance tumor destruction." (PMID 40076725, 2025). "A mechanism schematic diagram was drawn to illustrate the exosomal NKG2D receptor, which interacted with NKG2D ligands on tumor cells, and the IL24-mediated apoptotic pathways." (PMID 40076725, 2025). "A SARI‐antisense‐based approach was further employed to prove the pivotal role of SARI in IL‐24‐mediated anti‐tumor effects." (PMID 40338095, 2025). "While TXNIP and IL-24 act as tumor suppressors, STAT3 is considered an oncogene, being constitutively activated in nearly 70% of solid and hematological tumors." (PMID 40175348, 2025). "Mechanistically, IL-24 enhances anti-tumor immunity by promoting the secretion of pro-inflammatory cytokines e.g., Interferon (IFN-γ), Tumor necrosis factor (TNF-α), activating immune effector cells such as CD8+ T cells and NK cells." (PMID 40806452, 2025). "And in MLS, the presence of PRG4 has been observed to sustain the proliferation of tumor cells, which is achieved through the suppression of IL-24, a cytokine known for its antitumor properties." (PMID 39456230, 2024). "IL-24, a cytokine belonging to the IL-10 family, inhibited the growth of tumor cells and induced tumor-specific apoptosis." (PMID 38399342, 2024). "IL-24 selectively inhibits tumor cell growth, invasion, metastasis, and angiogenesis, induces cancer-selective apoptosis, stimulates the anticancer immune response, sensitizes cancer cells to treatment, and exerts antitumor effects through multiple pathways." (PMID 39456230, 2024). "One study combined the viral expression of tumor-suppressive miRNA-34 and IL-24 to improve an OV’s efficacy, and also compared the use of these approaches separately." (PMID 39204331, 2024). "IL-24 is recognized for its ability to suppress tumor invasion, metastasis, and the stemness of tumor stem cells." (PMID 39664443, 2024). "Immunohistochemistry study showed reduced infiltration of FoxP3+ Treg cells and increased numbers of CD4+ T-cells and cells expressing interleukin-12-beta-2 receptor (IL-12Rβ2+) and interleukin-24 (IL-24+) in the tumour from γT3-treated animals." (PMID 39416707, 2024). "IL24, part of the IL-10 cytokine family, is recognized as a tumor suppressor with significant anti-cancer properties." (PMID 39850884, 2024). "Mainly expressed in immune cells, interleukin 24 (IL24) exerts extensive tumor‐specific cytotoxic effects on a variety of malignancies without affecting normal cells." (PMID 38737469, 2024). "The construction of antibody-cytokine fusion proteins that target IL-24 at the tumor site holds significant potential in overcoming resistance and immune evasion." (PMID 39664443, 2024).
tumor (continued). "Inhibitory effects on tumor progression were observed by analyzing tumor growth and apoptosis induction, which indicates recombinant B. breve-IL24 is a promising strategy in cancer therapy." (PMID 38495751, 2024). "To date, a majority of studies have focused on establishing IL24 for cancer therapy to kill tumor cells, while some studies reported that rIL24 is not capable of activating peripheral NK cells." (PMID 38737469, 2024). "The interleukin 10 family, which includes IL-24, plays important roles in cell differentiation, apoptosis, and tumor growth, and thus represents an attractive therapeutic target." (PMID 37484532, 2023). "Mda-7/Interleukin-24 (IL-24) is a pleiotropic cytokine that has a specific tumor suppression potential that has attracted a lot of attention." (PMID 37280571, 2023). "The SCC microenvironment is rich in IL-6, IFN-γ, TGF-β, GM-CSF, and IL-24, which induce tumor growth and invasion." (PMID 36793738, 2023). "Accumulated evidence strengthened the concept of the “bystander effect” according to which secreted IL-24, either in normal or cancer cells, induces tumor apoptosis in presence of IL-20/IL-22 receptors." (PMID 37484532, 2023). "We and others have shown that induction of ceramide production plays a decisive role in IL-24-mediated apoptosis, with inhibition of ceramide production suppressing IL-24-induced apoptosis in several tumor cell lines." (PMID 37444474, 2023). "IL-24, a novel tumor suppressor, inhibits IL-24 expression in human PBMCs, increasing susceptibility to TB." (PMID 37946240, 2023). "The outcomes exhibited tumor suppressive activity and confirmed the tumor migration of iPSCs-derived MSCs-producing IL-24." (PMID 36742134, 2023). "Studies have shown that it can inhibit tumor growth by activating IL-24/PERP and suppressing atypical TGFβ signaling." (PMID 38097551, 2023). "MTT tests and LDH release assays were carried out in order to evaluate and figure out the tumor inhibition titer of Ad/IL-24 with respect to metabolic activity and cellular integrity." (PMID 37280571, 2023). "Several researches approved the stance of IL-24 as a novel and effective candidate for tumor immunotherapy due to its abilities in mediating direct anticancer activities and also impeding tumor angiogenesis and metastasis." (PMID 36742134, 2023). "As a novel cancer growth-suppressing and apoptosis-inducing gene, IL-24 plays a prominent role in inhibiting tumor growth." (PMID 35292065, 2022). "The current study also examined the impact of IL-10 on tumor regression induced by E7&IL-24, E7, or IL-24 in parallel with our main study by following up the tumor volume for up to six weeks." (PMID 35752792, 2022). "Due to the inhibiting effect of IL-2, IL-24 and IL-27 on EC cells, there are bright prospects for them to be used as anti-tumor drugs." (PMID 36531027, 2022). "Using the system, we simultaneously monitored the therapeutic effect of a novel gene therapy (a delivery of recombinant bacterial gene (IL-24-expressing strain), including the apoptotic and necrotic induction within the tumor in vivo." (PMID 35814447, 2022). "For example, the vaccinia virus expressing the IL-24 gene has been found to inhibit tumor cell growth by inducing oncolysis and apoptosis and stimulating anti-tumor immunity in breast cancer and colorectal cancer." (PMID 35371972, 2022). "Interleukin-24 (IL-24) is a novel tumor suppressor cytokine that selectively induces apoptosis in a wide variety of tumor types." (PMID 35814447, 2022). "The traditional delivery of IL-24 via liposomes or replication-defective adenovirus cannot target tumor cells, which limits its value for cancer gene therapy." (PMID 35292065, 2022). "The hUC-MSC with IL-24 (2 × 106) were administered ten days post tumor cell implantation via tail vein injection every week for three weeks." (PMID 35955703, 2022). "Meanwhile, fewer tumor blood vessels were observed in IL-24-Ishikawa group than in the Null-Ishikawa group." (PMID 36531027, 2022).